MTOR (mechanistic target of rapamycin kinase)
Diseases named in the same sentence as MTOR in open-access papers (continued):
Sharing a sentence is not in itself a finding about the gene and the disease.
Sepsis (continued). "The different expression of miRNA might potentially be used to discriminate septic AKI from sepsis-non AKI and they were correlated with the regulation of mitochondrial oxidative stress and dysfunction, including PGC-1α, SIRT1, mTOR, OXSR1 and NOX5." (PMID 28296904, 2017). "Other authors showed that an in vivo sepsis not induced by LPS inhibits mTOR signaling pathways in rat cardiac muscle and that this defect appeared mediated, either directly or indirectly, by the endogenous over production of TNF-α." (PMID 25169902, 2014). "Consequently, this investigation delves into the apoptosis and autophagy engendered by the PI3K/AKT/mTOR axis through both in vivo and in vitro studies, and provides an exhaustive portrait of PTX3’s influence on myocardial injury in sepsis and its underpinning mechanisms." (PMID 38784395, 2024). "The findings above imply that CTLA4 accumulation is accompanied by impaired autophagy and increased mTOR signaling pathway activity, there may be a regulatory link between mTOR, autophagy, and CTLA4 accumulation that impacts CD4+ T cell manifestation in sepsis." (PMID 39104632, 2024). "The second one is that blocking the PI3K/AKT/mTOR signaling pathway had a protective effect against sepsis, which is in line with our findings at 1d, 2d, 3d and 5d that administration of XBJ therapy suppressed p-PI3K, p-AKT and p-mTOR, showing by inhibition of the PI3K/AKT/mTOR pathway." (PMID 37219401, 2023). "The results indicated that Compound C or MHY1485 could partially reverse the ameliorated inflammation response and multi-organ injury induced by ω-3 PUFAs in sepsis, indicating that ω-3 PUFAs protected against sepsis by directly regulating the AMPK/mTOR pathway." (PMID 36694426, 2023). "We hypothesized that TFEB and SNAREs may play key roles in the modulation of A-L fusion by mTOR during sepsis, a possibility that has not been previously investigated." (PMID 35435531, 2022). "Studies have suggested that mTOR activation may suppress beneficial autophagy activity during severe stages of sepsis, but activation of autophagy in early sepsis may be independent of mTOR23, which is in line with our results in this study." (PMID 32694519, 2020). "By silencing the Phosphatase and tensin homolog protein in the cardiac cell, the signaling pathways (AKT/mTOR) were activated with the treatment of TG 50 mg/kg and TG 100 mg/kg, and this result suggested that inhibition of signaling pathway (PTEN-AKT/mTOR) by sepsis." (PMID 33260422, 2020). "Contrary to our hypothesis, however, a mild dietary restriction of Zn did not alter disturbances in protein synthesis, mTOR signaling, or protein degradation in the acute or chronic phases of sepsis." (PMID 27811170, 2016). "However, this exaggerated increase in the locally produced cytokine did not impact the sepsis‐induced decrease in muscle protein synthesis, mTOR signaling, or autophagy." (PMID 27811170, 2016). "Therefore, using rapamycin to modulate the mTOR signaling pathway could regulate the onset of ERS-induced cell apoptosis through autophagy and ultimately reverse the fate of CD4+ T cells in elderly sepsis." (PMID 40933998, 2025). "Additionally, in a mouse sepsis model induced by CLP, zinc finger antagonistic proteins have been discovered to induce cardiomyocyte pyroptosis by regulating the AMP-activated protein kinase (AMPK)/mTOR signalling pathway, exacerbating sepsis-induced cardiac dysfunction." (PMID 40520010, 2025). "Besides, the data supported the theory that the level of PTEN reduced and level of p-AKT and p-mTOR will be increased by the treatment of TG, and, by suppressing the PTEN, TG will activate the signaling pathway and protective effect of TG against the sepsis-induced myocardial dysfunction." (PMID 33260422, 2020). "The data also suggests that the activation of autophagy in early sepsis may be independent of mTOR." (PMID 30744190, 2019).
Sepsis (continued). "When it comes to the comparison between survivors and non-survivors of all the sepsis patients, the differences of ERS and mTOR mediated autophagic-lysosomal disorder markers were still significant." (PMID 40933998, 2025). "Second, we have to point out that we do not look into how changes to the PI3K/AKT/mTOR pathway XBJ work to affect cardiomyocyte apoptosis and autophagy during sepsis in further detail." (PMID 37219401, 2023). "In terms of metabolism and cell activation, expression of mTOR on CD4+ and CD8+ T cells in the sepsis group was significantly higher than that in the non-sepsis group." (PMID 35898496, 2022). "The MFI of CTLA-4, LC3II, mTOR, and P62 on CD4+ cells were significantly higher in patients with sepsis than in non-septic patients (185.5 versus 104.4, P<0.0001; 152.3 versus 99.6, P=0.001; 166.8 versus 143.6, P=0.029; and 244.0 versus 177.2, P=0.001, respectively)." (PMID 39104530, 2024).
acute myeloid leukemia (174 papers, 2010 to 2026). Acute myeloid leukemia (AML) is a group of neoplasms arising from precursor cells committed to the myeloid cell-line differentiation. "For example, constitutive and cytokine-mediated activation of the PI3K/Akt/mTOR signaling pathway is a common hallmark in patients with acute myeloid leukemia (AML), and regulation of this system is a feasible therapeutic option in the treatment of AML." (PMID 34953494, 2021). "Loss of LKB1 activates the mTOR pathway and promotes cell growth, survival and tumorigenesis in acute myeloid leukemia, squamous cell carcinoma of skin, and squamous cell carcinoma of lung via LKB1/AMPK regulation." (PMID 29228674, 2017). "Additionally our pathway analysis using SPIA identified three significant pathways, acute myeloid leukemia pathway, Insulin signaling pathway and mTOR signaling pathway, which are associated with BMD status." (PMID 26390436, 2015). "However, aberrant PI3K/Akt/mTOR signaling has been implicated in many human cancers, including acute myelogenous leukemia (AML)." (PMID 20671809, 2010). "Sirolimus targets the serine/threonine-protein kinase: mammalian target of rapamycin (mTOR), and GA has been associated with the Akt/mTOR signaling pathway, demonstrating antileukemic efficacy in acute myeloid leukemia (AML)." (PMID 38396979, 2024). "The constitutive hyper-activation of phosphatidylinositol 3-kinase (PI3K)/protein kinase B (Akt)/mammalian target of rapamycin (mTOR) signaling pathways has frequently been associated with acute myeloid leukemia (AML)." (PMID 27071307, 2016). "Triggering apoptotic factors such as TRAIL in cancer systems and suppression of Akt-mTOR signalling leading to maturation of acute myeloid leukaemia cells." (PMID 40427522, 2025). "Acute myelogenous leukaemia is a heterogeneous group of malignancies, and we know that the mTOR pathway plays a central role in their survival and proliferation." (PMID 40787757, 2025). "VLA-4 interacts with VCAM-1 to promote Akt, MAPK, NF-κB, and mTOR signaling, while reduce apoptosis in acute myeloid leukemia (AML) cells." (PMID 38736891, 2024). "We previously reported that PegC, in combination with the Bcl2 inhibitor venetoclax, inhibits protein synthesis through interference with cap-dependent mRNA translation downstream of mTOR signaling in acute myeloid leukemia (AML)." (PMID 38951899, 2024). "mTOR is constitutively activated in acute myeloid leukemia (AML) cells, as indicated by the phosphorylation of its substrates, 4EBP1 and P70S6K." (PMID 37237490, 2023). "In acute myeloid leukemia, high expression of PD-L1 was found to promote aerobic glycolysis via the Akt/mTOR/HIF-1α axis." (PMID 37649034, 2023). "Deoxyshikonin decreases cell viability and exhibits anti‐glycolytic activity in acute myeloid leukaemia cells by repressing the glycolytic enzyme pyruvate kinase M2 through inactivation of the Akt/mTOR pathway." (PMID 37155410, 2023). "Eventually, it was found that compound 27 can suppress in dose-relevant mode phosphorylation of both ERK1/2 and mTOR in FLT3-ITD acute myeloid leukemia cells." (PMID 37438819, 2023). "The abnormal activation of the PI3K/AKT/mTOR pathway can promote the proliferation of tumor cells and endow various malignant tumors, including acute myeloid leukemia (AML), with resistance to chemotherapy." (PMID 37907984, 2023). "Among the biochemical mechanisms abnormally elevated in malignancies, including acute myeloid leukemia, is the phosphoinositide 3-kinase-Akt-mammalian target of rapamycin route (PI3K-Akt-mTOR pathway)." (PMID 37047003, 2023). "Targeting the mTOR pathway reverses the bone marrow (BM)-mediated protection of FLT3-ITD acute myeloid leukemia (AML) cells from FLT3 inhibition." (PMID 36259537, 2022). "In line with this, CDK6 inhibition reduced the activity of MAP-ERK and PI3K/AKT/mTOR signaling pathways in an acute myeloid leukemia cell line." (PMID 36619863, 2022).
acute myeloid leukemia (continued). "(E) Model of ATM and mTOR-dependent survival of FLT3-ITD acute myeloid leukemia (AML) cells following FLT3 inhibition in BM microenvironment." (PMID 36259537, 2022). "In acute myeloid leukemia cells, origins of Kasumi-1 cells, the suppression of Akt/mTOR pathway induces activation of ERK pathway to compensate for pro-survival signal transduction." (PMID 33490663, 2021). "For example, it has been described that mTOR regulates cell survival after etoposide treatment in acute myeloid leukemia cells (AML)." (PMID 34681745, 2021). "ERK1/2 and AKT/mTOR mediated antileukemia effects of Gnetin C were also demonstrated in acute myeloid leukemia xenografts." (PMID 33255879, 2020). "The phosphatidylinositol 3-kinase (PI3K)-Akt-mechanistic target of rapamycin (mTOR) pathway is constitutively activated in human acute myeloid leukemia (AML) cells and is regarded as a possible therapeutic target." (PMID 31240133, 2019). "Inhibition of mRNA translation and induction of cell cycle arrest, apoptosis, and autophagy was seen in the treatment of acute myeloid leukemia and T-cell acute lymphoblastic leukemia cells with ATP mTOR inhibitors." (PMID 31817676, 2019). "A recent study has shown that foreign RNA-unliganded RIG-I inhibits the Src-facilitated activation of Akt-mammalian target of rapamycin (mTOR) in acute myeloid leukemia cells by competing with Src for recognition of Akt." (PMID 31088527, 2019). "Regarding the mechanisms of Src-enhanced chemoresistance, Src confers to AKT/MTOR activation in acute myeloid leukemia for cancer stemness, which is highly associated with drug resistance." (PMID 30473665, 2018). "Constitutive signaling through the phosphatidylinositol-3-kinase-Akt-mechanistic target of rapamycin (PI3K-Akt-mTOR) pathway is present in acute myeloid leukemia (AML) cells." (PMID 29382066, 2018). "Taken together, B392 can strengthen the effect of sirolimus on mTOR signaling and can enhance cytotoxicity in sirolimus-resistant acute myeloid leukemia (AML) cells." (PMID 28186963, 2017). "Activation of the PI3K/AKT/mTOR signaling pathway is prevalent in acute myeloid leukemia (AML), and constitutive activation of AKT is associated with inferior survival in AML." (PMID 28881728, 2017). "Therein, expression of the DEK-NUP214 fusion protein identified in acute myeloid leukemia increased mTORC1 activity in myeloid cells, leading to increased protein synthesis and proliferation that was attenuated by an mTOR inhibitor." (PMID 28558019, 2017). "The response of the ISN and of an AML (acute myeloid leukemia) cell population to mTOR inhibitors is studied here with reference to the dual ATP-competitive mTOR inhibitor AZD8055." (PMID 27149630, 2016). "Recent studies have shown that combinations of mTOR inhibitors with other drugs enhanced anti-leukemic activities in acute myeloid leukemia (AML) cells." (PMID 26919107, 2016). "In agreement with our findings, Nishiokaet al. showed that the HDAC inhibitor MS-275 was able to block Akt/mTOR signaling in acute myelogenous leukemia HL60 cells and acute promyelocytic leukemia cells." (PMID 26287365, 2015). "Aberrant activation of the PI3K/Akt/mTOR pathway is a common feature of acute myeloid leukemia (AML) patients contributing to chemoresistance, disease progression and unfavourable outcome." (PMID 26674543, 2015). "Previous studies have demonstrated that both Src and mTOR are often constitutively activated in acute myeloid leukemia (AML) cells and hence constitute potential therapeutic targets." (PMID 26061184, 2015). "Effects of the mTOR inhibitor rapamycin were characterized on in vitro cultured primary human acute myeloid leukemia (AML) cells and five AML cell lines." (PMID 23082251, 2012). "Moreover, it is known that gallic acid inhibits AKT/mTOR signaling, which leads to mitochondrial dysfunction, an energy crisis, and the death of acute myeloid leukemia cells." (PMID 40717210, 2025).
acute myeloid leukemia (continued). "It was also demonstrated that high PD-L1 expression could promote the glycolysis of acute myeloid leukemia cells through the Akt/mTOR signaling transduction pathway." (PMID 36980323, 2023). "Furthermore, dihydroartemisinin (DHA) effectively induced the ferroptosis of acute myeloid leukemia (AML) cells through autophagy by regulating the activity of AMPK/mTOR/p70S6k signaling pathway." (PMID 35635082, 2022). "It has been reported that exosomal miR-7-5p derived from BMSCs could negatively regulate OSBPL11 via PI3K/AKT/mTOR signaling pathway in acute myeloid leukemia (AML) and finally inhibit AML proliferation and promote apoptosis." (PMID 35300408, 2022). "mTOR-mediated upregulation of the PFKFB3 pathway is vital for acute myelogenous leukemia (AML)." (PMID 33671514, 2021). "In particular, DHA, a semi-synthetic derivative of artemisinin anti-malarial drug, accelerates ferritinophagy through the AMP-activated protein kinase (AMPK)/mammalian target of rapamycin (mTOR)/p70S6k signaling pathway to trigger ferroptosis in acute myeloid leukemia cells." (PMID 34831207, 2021). "The results of the functional analysis of distinct SCAMP and its co-expressed genes indicated that these genes were involved in multiple pathways related to tumorigenesis and progression, such as human T-cell leukemia virus 1 (HTLV-1) infection, acute myeloid leukemia, and mTOR signaling pathways." (PMID 34426610, 2021). "For example, the m6A methyltransferases METTL3/14 and WTAP could act as oncogenic factors by promoting the translation of several oncogenes including c-MYC, BCL2, PTEN, and mTOR in acute myeloid leukemia." (PMID 33584787, 2020). "Similarly, to other mTOR inhibitors, ciclopirox significantly enhanced the ability of PN to target acute myeloid leukemia by inhibiting the PN-induced activation of mTOR." (PMID 32823992, 2020). "Moreover, the ability of extract to target specific pathways, namely ERK1/2 and AKT/mTOR, was also identified in a mouse model of tumor angiogenesis and in acute myeloid leukemia (AML) xenografts." (PMID 31487842, 2019). "Constitutive activation of PI3K/mTOR signaling occurs in the majority of human acute myeloid leukemia (AML) and likely results from a variety of mechanisms, including alterations in cellular growth factors and mutations in FLT3, c-kit, and Ras pathway proteins." (PMID 24904824, 2014). "The PI3K/AKT and mTOR signaling pathways are activated in acute myeloid leukemia." (PMID 25628645, 2014). "Nonetheless, GPR132 agonist activation of a GPR132-Gs-PKA pathway interfered with mTOR signaling and promoted acute myeloid leukemia (AML) cell differentiation, suggesting a therapeutic approach to AML treatment." (PMID 40333742, 2025). "For example, mTOR activity in acute myeloid leukemia may decrease during tumor progression." (PMID 40353763, 2025). "Studies completed in acute myeloid leukemia (AML) models have revealed a role of mTOR activity in mediating LSD1 resistance." (PMID 41497449, 2025). "Another study in acute myeloid leukemia (AML) cell lines showed that targeted inhibition of mTOR led to sensitization of AML cells to Aurora kinase inhibitors." (PMID 37786827, 2023). "Furthermore, overexpression of the PI3K/AKT/mTOR pathway was related to acquired resistance to gemtuzumab ozogamicin in acute myelocytic leukemia cells, and PI3K/AKT/mTOR inhibitors could lead to re-sensitization of the resistant cells." (PMID 38057772, 2023). "DHA also induced ferroptosis of acute myeloid leukemia (AML) cells through autophagy by regulating the activity of the AMPK/mTOR/p70S6k signaling pathway." (PMID 36677534, 2023). "Therefore targeting key components of PI3K-Akt-mTOR signaling pathway may be an effective therapy method of acute myeloid leukemia." (PMID 36397112, 2022). "On the other hand, in esophageal squamous cell carcinoma (ESCC) and acute myeloid leukemia (AML) cells there was an opposite correlation between mTOR and PLK1 in autophagy." (PMID 35719948, 2022).